SPTBN2 (spectrin beta, non-erythrocytic 2)
Diseases named in the same sentence as SPTBN2 in open-access papers (continued):
Sharing a sentence is not in itself a finding about the gene and the disease.
cancer (10 papers, 2020 to 2024). A tumor composed of atypical neoplastic, often pleomorphic cells that invade other tissues. "The KEGG enrichment analysis performed suggests that SPTBN2 co-expression genes are mainly concentrated in pathways associated with cancer development, including “Pathways in cancers”, “Hematopoietic cell lineage”, and “P13K-Akt signaling pathway”." (PMID 38684762, 2024). "SPTBN2 expression was found to negatively correlate with almost all of the ICP genes in several cancers, including GBM and LGG." (PMID 38684762, 2024). "In summary, we innovatively performed a multi-omics pan-cancer analysis of SPTBN2 which provides strong evidence for the prognostic and immunological value of SPTBN2 in various tumors." (PMID 38684762, 2024). "In the present study, a novel exploration of the value and potential mechanism of SPTBN2 in PAAD was conducted using multi-omics in the background of pan-cancer." (PMID 38684762, 2024). "Considering the cancer-promoting effect of SPTBN2 in PAAD, we conducted a preliminary exploration of the biological function(s) of SPTBN2 at the genetic level." (PMID 38684762, 2024). "PID1 was recently identified as one of the two signature genes (the other gene is SPTBN2) in seven cancers." (PMID 35886011, 2022). "The expression levels of SPTBN2 were examined in various databases, including the Cancer Cell Line Encyclopedia (CCLE), Gene Expression Omnibus (GEO), and Human Protein Atlas (HPA)." (PMID 34745988, 2021). "SPTBN2 has been identified as one of the marker genes for the pathogenesis of cancer and plays an important role in the pathogenesis of cancer, which is of great significance for understanding the pathogenesis and early diagnosis of cancer." (PMID 34887379, 2021). "Combined with the role of SPTBN2 in the TME, we reasonably speculate that SPTBN2 may be a potential predictive biomarker of immunotherapy response in patients with malignant tumors such as PAAD." (PMID 38684762, 2024). "SPTBN2 is a protein-coding gene that is closely related to the development of malignant tumors." (PMID 38684762, 2024). "However, to date, while studies on the role of SPTBN2 in various cancers has been investigated, its role and molecular mechanism(s) in PAAD remain to be investigated in the context of pan-cancer." (PMID 38684762, 2024). "The mRNA expression levels of SPTBN2 in NSCLC ranked 13th among all examined cancer cell lines." (PMID 34745988, 2021). "Furthermore, OV patients in stage II, III, or IV shared similar gene expression patterns for SPTBN2 or BCL2L1 in cancer tissues." (PMID 34179092, 2021). "It should be mentioned that SPTBN2 and BCL2L1 were upregulated together not only in OV but also in various types of cancers, which were validated by various types of tumors and normal samples at both the gene and protein levels." (PMID 34179092, 2021). "To further validate the role of SPTBN2 in CC patients, we first analyzed the expression of SPTBN2 in TCGA-COAD database, and we found that SPTBN2 was significantly highly expressed in COAD patients and in a variety of cancers." (PMID 34544413, 2021). "Using the Genomics of Drug Sensitivity in Cancer dataset, an investigation of a possible correlation between SPTBN2 levels and drug sensitivity suggested that Vorinostat (a HDAC inhibitor) inversely correlates with SPTBN2 expression." (PMID 38684762, 2024). "First, despite exploring the expression and prognostic value of SPTBN2 in different cancer types, there are no clinical data to validate these findings." (PMID 38684762, 2024). "The most increased protein, spectrin β non-erythrocyte 2 (SPTBN2), is elevated in a variety of cancers and promotes cancer migration via a PI3K/AKT signaling pathway." (PMID 35852874, 2022).
neurodegenerative disease (7 papers, 2013 to 2024). A disorder of the central nervous system characterized by gradual and progressive loss of neural tissue and neurologic function. "Most studies mainly focused on the role of SPTBN2 in neurogenesis and degenerative diseases as a structural carrier for the stabilization and activation of membrane channels, receptors, and transporters." (PMID 34179092, 2021). "A recent study identified the causative mutation of canine neonatal cerebellar cortical degeneration in SPTBN2 (genome-wide mRNA sequencing) using only a single case of this neurodegenerative disease." (PMID 23531239, 2013).
neurologic disorders (4 papers, 2014 to 2023). "SPTBN2 was previously reported in the development of cognition and motion or neurologic disorders." (PMID 34179092, 2021). "The first 3 β-spectrin genes (SPTBN1, SPTBN2, and SPTBN4) are responsible of multiple neurologic disorders, depending on the gene and inheritance pattern." (PMID 36331550, 2023). "Variants in the spectrin genes SPTAN1, SPTBN1, SPTBN2, and SPTBN4 have been associated with neurological disorders; however, SPTBN5 gene-variants have not been associated with any human disorder." (PMID 35782384, 2022). "In addition, mutations in various members of the spectrin gene family are associated with erythroid cell disorders (SPTA1, SPTB) and neurological disorders (SPTAN1, SPTBN1, SPTBN2, and SPTBN4); however, no human genotype-phenotype correlation has been established for SPTBN5 to date." (PMID 35782384, 2022).
movement disorder (1 paper, 2024). Neurological conditions resulting in abnormal voluntary or involuntary movement, which may impact the speed, fluency, quality and ease of movement. "In a patient with an ataxic movement disorder, two variants of uncertain significance in the genes SPTBN2 and KCNC3 associated with SCA were detected." (PMID 39596509, 2024).
neurodevelopmental disorder (1 paper, 2023). A behavioral and cognitive disorder with onset during the developmental period that involves impaired or aberrant development of intellectual, motor, or social functions. "These more severe symptoms resemble those of the neurodevelopmental disorder SPARCA1 /SCAR14, caused by homozygous recessive SPTBN2 mutations." (PMID 37626910, 2023).
SPTBN2 also shares sentences with these, for which no sentence is quoted: cerebellar ataxia (5 papers); autosomal dominant cerebellar ataxia (2); breast cancer (2); cerebellar degeneration (2); cerebellar disorder (2); ovarian serous cystadenocarcinoma (2); progressive ataxia (2); schizophrenia (2); acquired ataxia (1); adenocarcinoma (1); Adult onset (1); ataxia telangiectasia (1); Boucher–Neuhauser Syndrome (1); ciliopathy (1); deafness (1); endocervical adenocarcinoma (1); essential tremor (1); focal segmental glomerulosclerosis (1); glioblastoma (1); GM2 gangliosidosis (1); head and neck carcinoma (1); Lung squamous cell carcinoma (1); lymph node metastasis (1); Marfan syndrome (1); pancreatic cancer (1); Parkinson disease (1); prostate carcinoma (1); retinal degeneration (1); Spinocerebellar Ataxia Autosomal Recessive 14 (1); stomach (1).
A further 5 diseases each share a sentence with SPTBN2 in 1 paper.